RNU5E-1 (RNA, U5E small nuclear 1)
Synonyms: U5E; RNU5E
Gene: Small nuclear RNA gene on chromosome 1 (11,908,152 to 11,908,272, forward strand). Ensembl gene ENSG00000199347.
Gene Ontology:
Biological process: formation of quadruple SL/U4/U5/U6 snRNP; spliceosomal tri-snRNP complex assembly
Cellular component: U4/U6 x U5 tri-snRNP complex; U5 snRNP